HIF1A (hypoxia inducible factor 1 subunit alpha)
Diseases named in the same sentence as HIF1A in open-access papers (continued):
Sharing a sentence is not in itself a finding about the gene and the disease.
cancer (continued). "AMPK and hypoxia-inducible factor (HIF)-1α are master regulators in the context of cancer-related aerobic glycolysis and oxidative phosphorylation." (PMID 33262773, 2020). "The DNA hydroxymethylase TET1 has been reported to be transcriptionally activated by HIF-1α in cancer cells." (PMID 31935962, 2020). "During the process, hypoxia-inducible factor 1α (HIF-1α) plays an essential role, and overexpression of HIF-1α has been observed in many human cancers." (PMID 32974385, 2020). "Many upregulated genes such as cancer stem cell marker (SOX2/9), hypoxia inducible factor (HIF1α), TGF-β signaling associated receptor (TGFBR2), and differentiation related transcription factor (RUNX2) were reported to promote tamoxifen resistance." (PMID 32420379, 2020). "This evidence convinces us that the nickel-induced ANGPTL4 or other oxidative stress-respond protein via ROS/HIF-1α are the reason of cell transform into cancer." (PMID 31963541, 2020). "The Hypoxia-Inducible Factor 1-alpha, HIF1a, is a master transcriptional regulator that controls oxygen delivery (via angiogenesis) and facilitates metabolic adaptation to hypoxia in cancer cells." (PMID 33255335, 2020). "The main way through which HIF-1α activity is upregulated in cancer is via the post-translational stabilization when the oxygen partial pressure drops below 10 mm Hg." (PMID 32932943, 2020). "Various signaling pathways are involved in inducing EMT in cancer including Notch, Wnt, transforming growth factor‐beta, HIF‐1α, and TNF‐α and extracellular matrix stiffness." (PMID 31725949, 2020). "Digoxin (a cardiac glycoside), used for treating congestive heart failure and arrhythmias, also inhibit HIF-1α synthesis and show anti-cancer effects and is in phase II of a clinical trial." (PMID 32824207, 2020). "HOTAIR was reported to be upregulated in cancer cells under hypoxic conditions and involved in HIF-1α regulation by acting as a ceRNA." (PMID 32640630, 2020). "One such compound, LW1564, significantly suppressed HIF-1α accumulation and inhibited the growth of various cancer cell lines, including HepG2, A549, and HCT116." (PMID 33235318, 2020). "In cell lines of both cancer types overexpression of LINK-A resulted in likewise increased HIF-1α levels and proliferation, migration and invasion." (PMID 32640630, 2020). "The α1 subunit of P4H (P4HA1) regulates the levels of 2-OG and succinic acid, suppressing the hydroxylation of proline in HIF-1α, thereby enhancing HIFα stability in cancer cells." (PMID 32928258, 2020). "This is because of HIF-1α, which is known to induce multidrug resistance in many types of cancer, such as breast and colon cancers." (PMID 32858793, 2020). "A recent study indicated that the TRAF6-H2AX-γH2AX- axis mediates HIF1α enrichment in the nucleus of cancer cells leading to its stabilization and activation to enhance tumorigenesis, glycolysis and metastasis." (PMID 31980706, 2020). "TWIST and HIF-1α are two key inducers of EMT in cancer cells, with the former being a downstream effector of HIF-1α." (PMID 33194655, 2020). "Hypoxia-inducible factor-1 alpha (HIF-1α) is a cancer-related transcription factor capable of the stimulation of enzymes involved in glycolysis." (PMID 32784981, 2020). "Collectively, the role of HIF-1α-induced miR-210 has different roles in various cancers, which need to be further explored to solve this mystery." (PMID 32014012, 2020). "It was proposed that Yap1 physically interacts with HIF1α with in cultured cancer cell lines, whereas HIF2α was shown was shown to enhance Yap1 activity without direct interaction of the two proteins." (PMID 31958058, 2020). "Accumulating data demonstrate that HIF-1α enhances the metastasis and proliferation of cancer cells." (PMID 32784981, 2020).
cancer (continued). "And, IL-6 increases angiogenesis by transcriptional upregulation of VEGF in JAK/STAT3 and hypoxia inducible factor 1α (HIF1α) dependent manner in cancer cells." (PMID 33351844, 2020). "On the other hand, numerous molecules that inhibit HIF-1α expression have been discovered or synthetized as a therapy for cancer." (PMID 33135539, 2020). "HIF-1α plays a key role in the regulation of proliferation, glucose metabolism, angiogenesis, invasion and metastasis, and multidrug resistance in cancer cells." (PMID 32631382, 2020). "HIF-1α activation has been shown to promote neo-angiogenesis and cell survival in several pathologies, including cancer." (PMID 33262987, 2020). "Hypoxia inducible factor-1alpha (HIF-1α) is a critical molecule that is overexpressed in many types of cancer; this transcription factor forms heterodimers consisting of an oxygen-dependent subunit (subunit α) and an independent oxygen subunit (subunit β)." (PMID 31947710, 2020). "HIF-1α induces some glycolytic enzymes including hexokinase and phosphofructokinase as well as glucose transferases (GLUTs) at the cell surface as HIF-1α inhibition has been one of the important strategies in cancer therapy." (PMID 33139969, 2020). "Chronic stress also promotes HIF-1α expression through a β2-AR-dependent pathway to drive cancer progression." (PMID 32973139, 2020). "EP was indeed shown to have the ability to increase HIF-1α production and glycolysis in a cancer cell line, which further substantiates our findings." (PMID 32916780, 2020). "It has been shown that HIF1α is overexpressed in some cancer types, especially in tissues with low oxygen concentration where it increases the glycolytic rate and the production of lactate." (PMID 32283712, 2020). "miR-373 has been found to bind to the 3’UTR of thioredoxin interacting protein (TXNIP) and downregulate its expression, which activates HIF-1α to promote cancer progression." (PMID 35006436, 2020). "Recent studies have revealed that hyper-activation of PI3K/AKT and HIF-1α in cancer cells plays a central role in glycolysis promotion." (PMID 32382009, 2020). "Hsc70 and Lamp2A knock-down led to an increase of HIF-1α protein level in cancer cell lines such as HeLa and Hep3b." (PMID 33643916, 2020). "The hypoxia inducible factor 1α, (HIF1α), on the other hand, is capable of inducing human embryonic stem cell (hESC)-like transcriptional program in cancer cells." (PMID 32226544, 2020). "Only HIF-1α can sense oxygen directly; it is stable under hypoxic conditions but under low-oxygen conditions it upregulates several genes to promote cancer cell survival." (PMID 33178201, 2020). "Although the increase in HIF1α protein levels was shown to be critical for the migration and metastasis of cancer cells, the mechanisms by which mtCa2+ regulates HIF1α protein levels are not clear." (PMID 32914752, 2020). "TGase 2 inhibition had a dominant inhibitory effect on anti-angiogenesis mediated by the regulation of HIF-1α in cancer cells." (PMID 32708896, 2020). "Some metabolic enzymes, such as succinate dehydrogenase (SDH), fumarate hydratase (FH), IDH and pyruvate kinase 2 (PKM2) are likely to activate HIF-1 pathway by stabilizing HIF-1α, therefore enhancing cancer metastasis." (PMID 33489906, 2020). "Increased miRNA-181c led to a decrease in mitochondrial oxygen consumption rate and ATP production in cancer cells with NRF2 mutation, leading to HIF-1α destability." (PMID 33109235, 2020). "We discuss how the transcription factors STAT3 and STAT5 participate in the regulation of energy metabolism and their involvement in the regulation of HIF-1α, an important regulator in the cancer hypoxic microenvironment." (PMID 31947710, 2020). "Malignant tumors overexpress MCT4, characteristic of metastatic cancer in association with HIF-1α upregulation." (PMID 32045997, 2020).
cancer (continued). "Among the HIF proteins, HIF-1α has been more characterized and discovered the signaling pathways involved in the cancer progression, which is due to its high overexpression in most of the solid tumors and their metastases." (PMID 32751958, 2020). "Consistent with the prior two studies, our results also showed that inhibition of HIF-1α by IDF-11774 had effects on cancer progression." (PMID 32847004, 2020). "Chemically or genetically inhibition of HIF-1α prevents chemo-resistance in many cancer cells in vitro and in vivo." (PMID 33290263, 2020). "Prior research found that exposure of cancer cells to chemotherapeutic drugs induced HIF-1α stabilization and activation in a reactive oxygen species (ROS)-dependent manner 12,13." (PMID 32194844, 2020). "HIF-1α, which is a regulatory factor involved in the cellular response to hypoxia, can promote glycolysis in cancer cells via the direct transcriptional activation of glycolysis related genes, including glucose transporters (GLUTs) and PKM2." (PMID 32000827, 2020). "Fourthly, PI3K/Akt also activates the downstream regulator of the mammalian target of rapamycin (mTOR) to further activate HIF-1α, so as to promote aerobic glycolysis, angiogenesis and neo-vascularization in cancer cells." (PMID 32631382, 2020). "The results of the test for HIF-1α indicate a decrease in the expression of this protein in cancer cells after incubation with celecoxib compared to controls." (PMID 31935820, 2020). "Recently, it was revealed that TAMs regulated aerobic glycolysis and apoptotic resistance of the malignant tumor via the EV transmission of HIF-1-α-stabilizing lncRNA (HISLA)." (PMID 32377504, 2020). "We also evaluated the prospective HRN biomarkers with potential for the diagnosis and prognosis of cancer, as well as the potential clinical applications related to the regulatory mechanisms shared between HIF-1α and ncRNAs in cancer treatment." (PMID 32014012, 2020). "Here, we also found the positive correlation between single HIF1A expression and glycolysis score in 18 cancer types (r = 0.17 ~ 0.52, p < 0.05), such as r = 0.45 in LUAD." (PMID 32635458, 2020). "Several reports show that hypoxia activates latent TGF-β1 via HIF-1α in hepatocytes, placental fibroblasts, primary human lung fibroblasts, smooth muscle cells and cancer cells." (PMID 32968152, 2020). "Hypoxia-inducible factor-1α (HIF-1α) has recently been found to participate in promoting the glycolytic metabolism in cancer cells." (PMID 32382009, 2020). "Hypoxia raises the proportion of BCSCs in a HIF-1α–dependent manner, which will contribute to cancer metastasis." (PMID 33489906, 2020). "In the context that HIF-1α knockout reduces the tumorigenicity and metastasis of cancer cells, HIF-1α has been a target molecule for the development of cancer therapy." (PMID 32752112, 2020). "Taken together, these results strongly indicate that CAV1 presence in different cancer cells reduces HIF1α activity and concomitantly target gene expression in hypoxia." (PMID 32825247, 2020). "In order to avoid this, in cancer cells HIF1α and HIF2α escape the proteasome-mediated degradation, which normally happens under normoxic conditions." (PMID 32365852, 2020). "It has been shown that cancer can elevate HIF-1α levels in both an oxygen-dependent and independent manner." (PMID 31437208, 2019). "It is noteworthy that both NEDD9 and SOX2 are recognized as HIF-1α downstream genes where they also participate in the control of cancer cell migration." (PMID 31462898, 2019). "Hypoxia induces ameboid motility and invasive phenotypes, mediated by HIF-1α in multiple cancer types." (PMID 31277295, 2019). "The significant role of HIF-1α in determining the outcome of cancer progression has been well documented." (PMID 30609861, 2019). "Based on these insights, hypoxia is a major driving force of the energetic reprograming of cancer cells, largely affecting glycosylation in a HIF-1α-dependent manner." (PMID 31157165, 2019).
cancer (continued). "There are no more literatures about HIF-2α-related ncRNA in CRC as well as GC, but a few studies have been reported to a lesser extent than HIF-1α in other cancers." (PMID 31817259, 2019). "CAIX and CAXII isoenzymes are considered as cancer-related adaptive factors and their upregulation was reported to be highly HIF1α-dependent." (PMID 31824854, 2019). "HIF-1α, a biomarker of the hypoxia microenvironment, demonstrates an emerging role in increasing resistance to current cancer therapies, including chemo−/radio-resistance." (PMID 31122265, 2019). "Cancer cells have high rates of glucose metabolism, which is regulated primarily by c-Myc, HIF-1α, and the glucose transporter 1 (Glut1)." (PMID 30967777, 2019). "The findings made with these cells also supported by the results for clinical samples, in which CX3CR1 and HIF-1α levels are elevated as cancers progress." (PMID 31077234, 2019). "By contrast, HIF-1α preferentially plays a role in reprogramming cancer metabolism by activating the transcription of glycolytic enzyme genes." (PMID 31817100, 2019). "HIF-1α also plays a role in many diseases, such as cancer, that generate a hypoxic microenvironment." (PMID 31744065, 2019). "Just as in cancer cells, HIF1α promotes glycolysis during reprogramming by increasing the expression levels of the glycolysis-related genes." (PMID 31067778, 2019). "This enzyme also acts as a transcriptional coactivator of HIF-1α in cancer cells, thus promoting glycolysis and inducing EMT." (PMID 31921862, 2019). "Sirtuin- (SIRT-3), phospho-mammalian target of rapamycin (p-mTOR) and hypoxia-inducible factor- (HIF-1α) are involved in metabolism and cancer." (PMID 30917505, 2019). "The hypoxia-inducible transcription factors 1α (HIF-1α) and 2α are broadly expressed in many human cancers, and expression of these proteins frequently correlate with poor patient prognosis." (PMID 31291975, 2019). "Among these molecules, Salternamide A inhibited the hypoxia-induced accumulation of HIF-1α in several cancer cell lines and suppressed the HIF-1α by downregulation of its upstream signaling pathways such as PI3K/Akt/mTOR, p42/p44 MAPK, and STAT3." (PMID 31906001, 2019). "In cancer, hypoxic condition is a common occurrence due to increased oxygen consumption resulting from rapidly growing cells, thus leading to HIF-1α activation." (PMID 30832444, 2019). "Together these results indicate that cardamonin inhibits cancer growth at least partially through targeting HIF-1α-mediated metabolic reprogramming in TNBC cells." (PMID 31455352, 2019). "HIF-1α, which is increased in many forms of cancer and can be activated by Tip60 and androgen, modulates energy metabolism in cancer cells by inducing over-expression of glycolytic enzymes including hexokinase (HK) and pyruvate kinase (PK)." (PMID 31671779, 2019). "CPT was demonstrated to suppress hypoxia-inducible factor 1 alpha (HIF-1α) -antisense RNA 1 in different human cancer types." (PMID 31208095, 2019). "HIF-1α gets stabilized under hypoxia, increasing aggressive phenotypes of cancer such as drug resistance and metastasis." (PMID 30791624, 2019). "It is proposed that activating HIF-1α initiates autophagy and aerobic glycolysis; this provides cells surrounding the cancer cells with the energy necessary to promote their growth." (PMID 30761299, 2019). "In both low- and high-grade cancers we observed significant correlations between Hif1α expression with Ldha (R = 0.97 for both), Mct4 (R = 0.99 and 0.94) and Vegf (R = 0.80 and 0.98)." (PMID 30813322, 2019). "An enhancement in the resistance of BC cells to tamoxifen and fulvestrant was observed in ERα+ cancer cells transfected with HIF1α." (PMID 31178825, 2019). "Main regulators of the glycolytic switch observed in cancer cells involve HIF-1α, c-Myc, Akt and mTOR." (PMID 31198853, 2019).
cancer (continued). "Hypoxia induces cellular responses during cancer progression, including the overexpression of CA IX due to HIF-1α and HIF-1β stabilization through the protein kinase A (PKA) signaling pathway." (PMID 31208095, 2019). "Overexpression of HIF-1α, MDR1 and LAPTM4B has been associated with poor disease outcome in many cancers when studied individually at tissue level." (PMID 30746305, 2019). "Previous studies have shown that HIF-1α upregulates genes involved in cancer invasion under hypoxia, and ROS generation is known to increase HIF-1α stability via PHD2 inactivation." (PMID 30808977, 2019). "There was a high expression of HIF-1α observed in peripheral blood of breast (2.389 ± 0.1597), ovarian (2.647 ± 0.1541), prostate (2.689 ± 0.2272) and colon (2.369 ± 0.1810) cancer patients as compared to healthy controls (0.1806 ± 0.1236)." (PMID 30746305, 2019). "Cancer cells have also developed O2-independent mechanisms to stabilize HIF-1α under normoxia and drive tumorigenesis, highlighting the essential pro-glycolytic role of this transcription factor." (PMID 31121959, 2019). "Some cancers display a competition between the repressive HIF-1α and activating c-Myc transcription factors at the E-box of the promoter." (PMID 35582579, 2019). "These compounds inhibit the accumulation of hypoxia-inducible factor-1α (HIF-1α), which is a drug target in hypoxia-adapted cancer cells, under hypoxic conditions." (PMID 30857246, 2019). "The increased stability and activation of HIF-1α in cancer cells contributes to altered glycolytic metabolism, invasion, and metastasis." (PMID 31195298, 2019). "Hypoxia is also an independent oncogenic driver and both KDM3A and KDM4B are co-activators of HIF-1α signalling in multiple cancer types." (PMID 31390833, 2019). "A large amount of studies have paid close attention to the expression of HIF-1α in the prognosis of various cancers including breast cancer, esophageal squamous cell carcinoma, hepatocellular carcinoma, gastric cancer, and lung cancer." (PMID 30782196, 2019). "In the hypoxia-independent pathway, increased oncogenic signaling in cancer cells induces HIF-1α expression." (PMID 31437208, 2019). "Whereas, hypoxia can induce expression of many oncogenes and suppress tumor suppressor genes, the overexpression of HIF-1α contributes to the initiation and progression of various cancers." (PMID 31497532, 2019). "In these conditions, TAMs will be exposed to lactic acid produced by the cancer cells, stabilizing HIF-1α, even in the presence of increased oxygen levels." (PMID 31906243, 2019). "Impaired mitochondria activate downstream signaling pathways such as HIF-1α and NFATc2, and downregulates the expression of Kv1.5 in cancer cells and proliferating VSMCs." (PMID 31083380, 2019). "The APEX1 stimulates numerous transcriptional factors that are involved in cancer promotion and progression, such as HIF-1α, nuclear factor kappa B (NFκB)." (PMID 31454981, 2019). "The discovery of small molecule HIF-1α inhibitors is an attractive approach in the development of cancer therapeutic drugs." (PMID 30678221, 2019). "Mutation in the chromosome region maintenance 1 (CRM1) binding domain of TXNIP suppresses HIF-1α nuclear export in cancer cells." (PMID 31615975, 2019). "The accumulation of HIF-1α has been documented in a variety of malignant tumors, including melanoma." (PMID 30804329, 2019). "IL-1β increases inflammatory signaling and enhances epithelial-mesenchymal transition in cancer cells through the IL-1β/HIF-1α/COX2 axis, which promotes the invasive capacities of tumoral cells in a hypoxic microenvironment." (PMID 31507607, 2019). "In general, there was 12–13 fold increase in expression of HIF-1α in all the studied cancer patients." (PMID 30746305, 2019).